BMI1P1 (BMI1 proto-oncogene, polycomb ring finger pseudogene 1)
Synonyms: lnc-OPHN1-5
Gene: Processed pseudogene on chromosome X (67,791,955 to 67,792,895, reverse strand). Ensembl gene ENSG00000234201.
Diseases named in the same sentence as BMI1P1 in open-access papers:
BMI1P1 is named in the same sentence as 4 diseases in open-access papers, as found by Europe PMC text mining. Sharing a sentence is not in itself a finding about the gene and the disease. The quoted sentences say what the papers report.
leukemia (2 papers, 2016 to 2020). A malignant (clonal) hematologic disorder, involving hematopoietic stem cells and characterized by the presence of primitive or atypical myeloid or lymphoid cells in the bone marrow and the blood. "Our earlier study indicated that BMI1P1 is frequently down-regulated in AML patients and low-expressed BMI1P1 of AML patients had obviously shorter leukemia-free survival (LFS) and OS than high-expressed." (PMID 32436945, 2020).
cancer (1 paper, 2016). A tumor composed of atypical neoplastic, often pleomorphic cells that invade other tissues. "BMI1(the parental gene of BMI1P1), a stem cell factor, was observed to be highly expressed in various types of human cancers, including AML." (PMID 27329719, 2016). "BMI1 pseudogene, namely BMI1P1, located on human chromosomal band Xq12, which has high homology with BMI1, has barely been studied in any cancers." (PMID 27329719, 2016). "Unfortunately, limited information is available to describe the function of BMI1P1, which has never been reported as a tumor suppressor in any human cancer." (PMID 27329719, 2016).
tumor (1 paper, 2016). "However, we showed that AML patients with a high BMI1P1 expression have a favorable outcome, suggesting that pseudogene BMI1P1 might be a tumor suppressor." (PMID 27329719, 2016).
BMI1P1 also shares sentences with these, for which no sentence is quoted: acute myeloid leukemia (1 paper).